PCDHA12 (protocadherin alpha 12)
Description:
Potential calcium-dependent cell-adhesion protein. May be involved in the establishment and maintenance of specific neuronal connections in the brain.
Synonyms: PCDH-ALPHA12
Tractability: Antibody: UniProt places it where antibodies can reach, with medium confidence; UniProt predicts a signal peptide or a membrane-spanning region; its Gene Ontology location is reachable by antibodies, with medium confidence; the Human Protein Atlas places it where antibodies can reach. PROTAC: its protein half-life has been measured.
Gene: Protein-coding gene on chromosome 5 (140,875,302 to 141,012,347, forward strand). Ensembl gene ENSG00000251664.
Subcellular location: Cell membrane
Subcellular location (Human Protein Atlas): Cytosol; Plasma membrane
Gene Ontology:
Molecular function: cell adhesion molecule binding; calcium ion binding
Biological process: cell adhesion; homophilic cell-cell adhesion; nervous system development
Cellular component: plasma membrane; membrane
Genetic constraint (gnomAD): Loss-of-function variants: 44 observed, 60.95 expected, observed/expected ratio (o/e) 0.72, 90% interval 0.57 to 0.93. The upper end of that interval is the gene's LOEUF score, 0.93, which puts it in group 3 of 6, group 1 being the genes least tolerant of losing a copy. Missense variants: 1,266 observed, 1,295.3 expected, observed/expected ratio (o/e) 0.98, 90% interval 0.93 to 1.02. Synonymous variants: 558 observed, 574.94 expected, observed/expected ratio (o/e) 0.97, 90% interval 0.9 to 1.04.
Homologues: Paralogues in human: PCDHA10 (83% identical), PCDHA11 (81% identical), PCDHA13 (81% identical), PCDHA8 (81% identical), PCDHA6 (81% identical), PCDHA2 (81% identical), PCDHA4 (81% identical), PCDHA1 (80% identical), PCDHA3 (80% identical), PCDHA7 (80% identical), PCDHA5 (80% identical), PCDHA9 (80% identical), and 49 more.
Diseases named in the same sentence as PCDHA12 in open-access papers:
PCDHA12 is named in the same sentence as 3 diseases in open-access papers, as found by Europe PMC text mining. Sharing a sentence is not in itself a finding about the gene and the disease. The quoted sentences say what the papers report.
tumor (2 papers, 2010 to 2023). "Our study identified cadherins (protocadherin-16 and protocadherin alpha-12) and alpha-2 catenin in primary tumor cells (BxPC-3) but not in metastatic tumor cells (AsPC-1), suggesting a defect in cell-to-cell adhesion in metastatic AcPC-1 cells." (PMID 20831833, 2010).
PCDHA12 also shares sentences with these, for which no sentence is quoted: cancer (1 paper); metastatic tumor (1).